HIF1A (hypoxia inducible factor 1 subunit alpha)
Diseases named in the same sentence as HIF1A in open-access papers (continued):
Sharing a sentence is not in itself a finding about the gene and the disease.
breast cancer (continued). "Although hypoxia is one of the most significantly upregulated pathways by DFP and JIB-04, we observed that both compounds significantly downregulated HIF-1α in both breast cancer lines." (PMID 41279823, 2025). "Whole lactoferrin can down-regulate the expression of HIF-1α, improve the hypoxic microenvironment of breast cancer, and promote radiation-induced DNA damage, improving the radiotherapy effect of breast cancer." (PMID 41293165, 2025). "One example is the activation of the PI3K/Akt/mammalian target of rapamycin (mTOR)-mediated HIF-1α pathway, as seen in many solid tumors, including colon cancer, prostate cancer, and breast cancer." (PMID 41585262, 2025). "The inhibition of ERRα impacts multiple downstream pathways, including those regulated by HIF-1α, thereby increasing the potential value of ERRα-directed therapies in treating aggressive breast cancer." (PMID 40723264, 2025). "Withaferin A, a steroidal lactone derived from Withania somnifera (ashwagandha), has demonstrated the ability to decrease HIF-1α production in breast cancer cells (MDA-MB-231)." (PMID 40004215, 2025). "In the case of some other cancer diseases, such as breast cancer, it has been shown that HIF-1α plays a dominant role in the development of cancer angiogenesis." (PMID 40429943, 2025). "Using the breast cancer mRNA data deposited in the TCGA database, we detected positive correlations between the levels of HIF-1α and HIF-2α, between HIF-1α and its target CAIX, and between HIF-2α and its target PAI-1." (PMID 40918648, 2025). "Elevated levels of HIF-1α have been detected in both tissue and plasma samples of breast cancer patients, correlating with tumor size, grade, and lymph node involvement." (PMID 40901111, 2025). "This pathway of EGFR activation has already been demonstrated in breast cancer, and HIF-1α reportedly induces HB-EGF shedding by ADAM12." (PMID 41346909, 2025). "In summary, our study establishes ERRα as a critical co-regulator of HIF-1α–driven transcription under hypoxic conditions in breast cancer, promoting both VEGF gene induction and chemoresistance through P-gp upregulation." (PMID 40723264, 2025). "Relative to other breast cancer subtypes, TNBC is commonly associated with increased HIF-1α levels, and consequently, HIF-1α has emerged as a promising drug target in TNBC." (PMID 40806629, 2025). "Overall, these anti-VM miRNAs interfere with multiple oncogenic pathways, including IL-6/STAT3, AXL, ZEB1, and HIF-1α, underscoring the multifaceted regulatory landscape of miRNA-mediated VM control in breast cancer." (PMID 41400702, 2025). "In basal breast cancer cases with a high WWOX/HIF1A ratio, pathways favouring oxidative phosphorylation (Complexes I–V: NDUFA/B/C/S/V, SDHC, COX, ATP6 family) were enriched, reducing reliance on glycolysis and limiting tumour proliferation." (PMID 41007296, 2025). "HIF-1α expression was significantly greater in high-grade and low-PR tumors (p < 0.05), reflecting its well-established role in aggressive breast cancer phenotypes." (PMID 40723264, 2025). "For example, the neuromedin B receptor (NMBR), a bombesin receptor subtype closely related to GRPR, was found to be transcriptionally upregulated under hypoxic conditions via HIF-1α in breast cancer cells." (PMID 41226822, 2025). "In breast cancer, hypoxia‐induced HIF‐1α upregulation is accelerated by a cascade including ROS, PI3K/ERK upregulation, and Rac1 signaling, causing upregulation of VEGF and enhanced tumor aggressiveness." (PMID 40740483, 2025). "Hirudin inhibits hematogenous metastasis of breast cancer through suppression of HIF-1α-controlled DSG2-mediated desmosome junctions, ultimately leading to the disintegration of CTC clusters." (PMID 41381723, 2025). "(2019) demonstrated the therapeutic effect of targeting the ROS/PI3K/AKT/HIF‐1α/HK2 axis in breast cancer." (PMID 40415238, 2025).
breast cancer (continued). "It is found to promote HIF-1α (Hypoxia-inducible factor-1α) to inhibit the expression of VEGF in breast cancer cells substantially and also interacted with VEGF receptor-2 (VEGFR-2) to block its kinase action." (PMID 40599794, 2025). "Through HIF-1α, hypoxia affects various genes, cytokines, chemokines, signaling pathways, and metabolic products through HIF-1α, further influencing immune cells and ultimately leading to immune evasion in breast cancer." (PMID 40813760, 2025). "Digoxin, a recognized cardiac glycoside, diminishes autophagy by downregulating HIF-1α expression in breast cancer cells at concentrations ranging from 50 to 100 nM." (PMID 40004215, 2025). "Dauricine suppressed the angiogenesis in human breast cancer by suppressing the expression of vascular endothelial growth factor and the accumulation of hypoxia-inducible factor 1α (HIF-1α) protein." (PMID 40422202, 2025). "Our findings were further confirmed by in vivo studies showing a significant decrease in HIF-1α expression in breast cancer syngrafts." (PMID 41514626, 2025). "Next, we examined 2-ANPC for its antitumor and HIF-1α-inhibitory activities using the 4T1 breast cancer syngraft model." (PMID 41514626, 2025). "For example, circPFKFB4, which is induced by HIF1α, has been shown to accelerate breast cancer progression by promoting p27 degradation." (PMID 41301888, 2025). "Data support that WWOX inhibits excessive HIF1α transactivation, acting as a protective factor, a mechanism that is impaired in breast cancer." (PMID 41007296, 2025). "HK also inhibited tumor growth by inducing apoptosis and suppressing HIF-1α-mediated glycolysis in human breast cancer cells." (PMID 41296425, 2025). "In breast cancers under hypoxic conditions, SULF1 is downregulated by HIF-1α, promoting cancer cell migration and invasion, in aggressive breast cancer cell lines." (PMID 41373732, 2025). "Recently, we demonstrated that EVs released by adipocytes increased breast cancer aggressiveness via HIF-1α, which is strictly related to breast cancer chemoresistance." (PMID 39863855, 2025). "Our TMA analysis bridges the gap between mechanistic in vitro findings and clinical relevance by demonstrating that ERRα expression positively correlates with PGC-1α and HIF-1α in breast cancer tissues." (PMID 40723264, 2025). "The overexpression of HIF-1α contributes to increased tumor proliferation by elevating the level of Ki67 in breast cancer." (PMID 40552278, 2025). "Some of its components have been shown to have anti-breast cancer effects, such as Alpinetin’s dependence on the ROS/NF-κB/HIF-1α axis to inhibit breast cancer growth." (PMID 40093330, 2025). "2-ANPC’s potency in downregulating HIF-1α was also shown in vivo by using the 4T1 breast cancer syngraft model." (PMID 41514626, 2025). "One study found that hypoxia-induced miR-153 regulated the HIF1α/VEGFα axis in breast cancer angiogenesis and proposed an opportunity of miR-153 as an anti-angiogenesis therapy." (PMID 40195216, 2025). "Collectively, these findings offer clinical evidence that ERRα collaborates with HIF-1α to promote hypoxia-induced P-gp expression, contributing to breast cancer chemoresistance." (PMID 40723264, 2025). "Several small molecule inhibitors, such as digoxin and PX-478, have shown potential in preclinical models of breast cancer by reducing HIF-1α stabilization and decreasing angiogenesis." (PMID 40851994, 2025). "In vitro investigations utilizing MCF-7 breast cancer cells have shown that resveratrol suppresses HIF-1α expression, which is essential for cancer cells to adapt to hypoxic environments." (PMID 40004215, 2025). "In this study, we investigated the molecular and functional interactions between HIF-1α and ERRα in breast cancer models and clinical samples to identify potential therapeutic strategies for enhancing treatment efficacy and overcoming drug resistance." (PMID 40723264, 2025).
breast cancer (continued). "Studies have also showed a correlation between miR-206 and HIF-1α in other diseases, such as colorectal cancer, lung cancer, and breast cancer." (PMID 38446322, 2025). "A previous study from breast cancer showed HIF1α upregulated IGF1R expression, and promoted cancer cells proliferation, invasion and chemotherapy-resistance." (PMID 40290443, 2025). "This inverse relationship between WWOX and HIF1α highlights the key link between loss of WWOX and enhanced Warburg effect in breast cancer." (PMID 41007296, 2025). "The stability of HIF-1α in breast cancer cells is regulated by microRNA-31, leading to enhanced autophagy." (PMID 40004215, 2025). "This study assessed the prognostic significance of the WWOX/HIF1A ratio in various cancers: breast cancer subtypes, glioblastoma multiforme, low-grade glioma, and hepatocellular carcinoma." (PMID 41007296, 2025). "Doxorubicin, a commonly utilized anticancer agent, inhibits HIF-1α activity and diminishes autophagic survival in breast cancer at concentrations ranging from 0.1 to 5 μM." (PMID 40004215, 2025). "In breast cancer, HIF-1α and HIF-2α play distinct but complementary roles in regulating tumor progression." (PMID 40901111, 2025). "In basal-like breast cancer, we found that a low WWOX/HIF1A ratio is associated with particularly aggressive disease because it promotes EMT via ZEB1 and ADAM9, facilitates ECM remodelling via MMP2 and ITGA1, and enables immune evasion via NOTCH1 and TLR4." (PMID 41007296, 2025). "Rg3, as a treatment for breast cancer, suppresses the self-renewal of breast cancer stem cells by blocking Akt-mediated HIF-1α activation, thereby eliminating their stemness and inhibiting tumor proliferation." (PMID 41585262, 2025). "A feed-forward loop exists between TAMs and tumor cells, as lactate upregulates HIF-1α-stabilizing long noncoding RNA (HISLA) in macrophages, subsequently inhibiting the hydroxylation and degradation of HIF-1α in breast cancer." (PMID 41373022, 2025). "It has been revealed that hypoxia activates the hypoxia-inducible factor 1-alpha (HIF1α)/vascular endothelial growth factor A (VEGF-A) axis in breast cancer to promote angiogenesis." (PMID 41148827, 2025). "Although CYP1B1 is considered to have an inhibitory effect on many malignant tumors, HIF-1α can affect the expression of CYP1B1 by activating estrogen receptor α in breast cancer." (PMID 40989158, 2025). "The expression of HIF-1α is regulated by microRNA-424, leading to the suppression of autophagy in breast cancer cells." (PMID 40004215, 2025). "A previous investigation using MnPI also showed decreased protein expression of 8-OHdG and HIF1α in orthotopic 4T1 breast carcinomas in 20 Balb/c mice, indicating a reduction in hypoxia and oxidative stress in this model." (PMID 40427469, 2025). "In breast cancer (BC), miR-561-3p has been shown to downregulate PD-L1 expression by repressing certain oncogenes associated with breast cancer such as ZEB1, HIF1A and MYC." (PMID 39941003, 2025). "This study provides the knowledge of the crosstalk potential of exosomes and highlighted the promising application of HIF‐1α inhibitor in breast cancer." (PMID 39107958, 2024). "Inhibition of HIF-1α leads to an increase in miR-30a, which disrupts the process and subsequently reduces the metastatic potential of breast cancer cells." (PMID 38339408, 2024). "Collectively, these findings in our study demonstrate that the ERα/HIF-1α/UBE2M axis is an oncogenic cascade regulating the development of breast cancer." (PMID 39138151, 2024). "Overall, this study proposes that isonahocol D2 would be the best drug candidate against the HIF1A therapeutic target for the metastasis of OSCC from breast cancer." (PMID 39458948, 2024). "Previous studies have shown that the activation of p38 MAPK and HIF-1α promotes the metastasis of breast cancer cells." (PMID 39049021, 2024).
breast cancer (continued). "In breast cancer, HIF‐1α plays an essential role in macrophages to promote tumor angiogenesis through ECs co-cultured with wild-type or HIF-1α-knocked out macrophages." (PMID 38602536, 2024). "Resveratrol analogue HS-1793 improves tumor tissue perfusion and hypoxia status under low oxygen conditions by inhibiting HIF-1α, suppressing angiogenesis, and enhancing radiosensitivity in mouse breast cancer cells." (PMID 38993643, 2024). "HIF1A emerged as the target predicted by all target prediction tools and miR-18a dependent HIF-1α and hypoxic regulation has already been reported in basal breast cancer previously." (PMID 38786043, 2024). "In breast cancer, DNA hypomethylation of the promoter region of HIF1A was found in breast cancer epithelial cells with highly malignant biological behavior." (PMID 38928200, 2024). "Previous research had shown that overexpression of HIF-1α has been observed in multiple types of tumors, such as liver cancer, breast cancer, brain cancer, BCa, and other tumor tissues, which can be regulated by tumor-related signaling." (PMID 39309474, 2024). "Subsequently, this epigenetic modification resulted in decreased expression of Nrf2 and HIF-1α, significantly promoting apoptosis in breast cancer cells and reducing radiation resistance in breast cancer." (PMID 38993643, 2024). "PDK1 is highly expressed in breast cancer tissues and its knockdown results in impaired growth and motility of breast cancer cells, in addition to inhibiting HIF-1α signalling." (PMID 39282472, 2024). "The roles of hypoxia-reprogrammed TCA cycles in promoting human breast cancer cell growth via a HIF-1α-mediated PCK2 pathway have been reported." (PMID 38729966, 2024). "Under hypoxic conditions, OPN triggers integrin-linked kinase (ILK)/Akt-mediated NF-κB activation, which results in HIF-1α-dependent VEGF expression in breast cancer cells and subsequent angiogenesis." (PMID 39062100, 2024). "Because HIF1α is also known to promote metastasis in breast cancer cells, For metastasis genes, snail is one of the key genes to promote EMT and metastasis progress, which is upregulated by HIF1α33." (PMID 38658533, 2024). "Wogonin can epigenetically regulate the Keap1 gene, inhibiting the Nrf2/HIF-1α pathway, inducing apoptosis in breast cancer cells, and alleviating acquired radioresistance." (PMID 38993643, 2024). "One study showed that the expression of OGT and elevated levels of HIF-1α are correlated with poor patient outcomes in breast cancers." (PMID 38732122, 2024). "HIF1α is a common component of pathways involved in the enhancement of breast cancer chemotherapy resistance and metastasis by facilitating breast cancer stem-like cell (BCSC) phenotypes." (PMID 38520019, 2024). "Parkin interacts with HIF-1α and promotes HIF-1α degradation through ubiquitination, inhibiting breast cancer cell metastasis." (PMID 38769340, 2024). "Conversely, a significant reduction in the HIF1α mRNA level was observed in breast cancer cells exposed to hypoxic conditions." (PMID 39532855, 2024). "For instance, HIF-1α-stabilized lncRNA encapsulated in extracellular vesicles of TAMs can regulate aerobic glycolysis in breast cancer cells." (PMID 39588377, 2024). "Our results unequivocally establish that miR-622 directly targets the 3′-UTR of HIF-1α mRNA in breast cancer cells." (PMID 38339408, 2024). "Targeting MMPs, cathepsins, integrins, and HIF-1α have been extensively studied in breast cancer treatment, and they show promising potential for clinical application potential." (PMID 39684583, 2024). "They demonstrated that breast cancer cells release high levels of exosomes and miR-210 in hypoxic exosomes in an HIF-1α-dependent manner." (PMID 39063226, 2024). "Under hypoxic stress, HIF-1a rapidly accumulates and activates hundreds of genes including MMPs in breast cancer patients." (PMID 39132498, 2024).
breast cancer (continued). "Immunoblotting of mammary tumour chunks showed dramatic upregulation of HIF1α that was concomitant with increased VIM, SNAI1, TWIST and decreased E-CAD expression in GPx2 KD relative to control tumours." (PMID 38238426, 2024). "In a preclinical study, a chlorine e6-encapsulated oxygen nanocarrier was tested on 4T1 murine breast cancer cells, demonstrating significant inhibition of HIF-1α activity by providing oxygen supply to the TME." (PMID 39459028, 2024). "miR-153 inhibits tumor angiogenesis by suppressing the HIF1α/VEGFA axis through binding to the 3′-UTR of HIF1A mRNA in breast cancer cells." (PMID 38468244, 2024). "Here we show in human breast cancer cells, that within 3 h of hypoxia exposure, glycolytic flux increases in a HIF1α-independent manner but is limited by NAD+ availability." (PMID 38485816, 2024). "HIF-1α significantly contributes to tumor development and progression, including breast cancer, through its pivotal roles in response to hypoxic conditions within tumors." (PMID 38842687, 2024). "The overexpression of hypoxia-inducible factor-1α (HIF-1α) is also closely related to drug resistance and prognosis in breast cancer patients." (PMID 38799423, 2024). "The algal metabolite enhanced the degradation of HIF-1α in breast cancer T47D cells, with an IC50 value as low as 0.4 μM, exhibiting selective anticancer effects under hypoxic conditions without affecting normoxic cell growth." (PMID 38667760, 2024). "This enhances HIF-1α transactivation and increases glucose uptake and lactate production in breast cancer cells." (PMID 38408962, 2024). "The study demonstrated that HIF1A plays a pivotal role in the metastatic advancement of OSCC originating from breast cancer." (PMID 39458948, 2024). "HIF-1α is highly expressed in breast cancer cells, while HIF-2α is highly expressed in endothelial cells." (PMID 38729948, 2024). "We found that PDK1 was highly expressed in breast cancer tissues, and PDK1 knockdown reduced the proliferation, migration, and tumorigenicity of breast cancer cells and inhibited the HIF-1α (hypoxia-inducible factor 1α) pathway." (PMID 38560503, 2024). "In this study, we found that TNFAIP2 is essential for HIF1α transcriptional expression, thereby facilitating breast cancer angiogenesis." (PMID 39532855, 2024). "Concurrently, PDK1, as a classical downstream target gene of HIF-1a, formed a positive feedback loop with HIF-1a to promote the progression of breast cancer." (PMID 38560503, 2024). "This highlights HIF1A’s crucial role in promoting breast cancer metastasis, suggesting it is a potential target for therapeutic intervention." (PMID 39458948, 2024). "Data from several clinical research revealed that in breast cancer, HIF1α’s role is particularly pronounced." (PMID 39697237, 2024). "Another study revealed that TAMs mediate aerobic glycolysis and chemoresistance in tumor cells via lncRNAs that shuttle HIF1α to breast cancer cells." (PMID 39403606, 2024). "Nevertheless, the link between HIF-1α expression and poor disease-free survival for ERα positive breast cancer patients is apparent, and should be further investigated." (PMID 39282472, 2024). "A preliminary study analyzing HIF-1α levels in tumor specimens showed that HIF-1α levels were elevated in 69% of metastatic breast cancers, while only 29% of primary breast cancers exhibited elevations in HIF-1α levels." (PMID 38424190, 2024). "HIF-1α not only enhances the expression of angiogenic factors but also influences breast cancer progression by regulating the composition and physical properties of the ECM." (PMID 39684583, 2024). "Under the purview of literature study, the objective of the current study was to explore the role of SULT1E1 and HIF1α proteins/genes expressions in human breast cancer tissues in relation to this disease severity." (PMID 39132498, 2024).